CTLA4 (cytotoxic T-lymphocyte associated protein 4)
Diseases named in the same sentence as CTLA4 in open-access papers (continued):
Sharing a sentence is not in itself a finding about the gene and the disease.
tumor (continued). "Similarly to the CTLA-4/CD28 dynamic, TIGIT outcompete DNAM-1 (CD226) and CD96 for the binding of CD155, impeding DNAM-1 positive co-stimulation and delivering a direct inhibitory signal as shown in TIGIT-deficient mice with delayed tumor growth." (PMID 34572799, 2021). "Likewise, CTLA-4 and PD-1 immune checkpoints, since they block the immune system’s recognition of cancer cells, could also be comparable as tumor suppressors." (PMID 33809974, 2021). "Main targets are the immune checkpoints cytotoxic T lymphocyte antigen 4 (CTLA-4) and programmed cell death 1 (PD-1), receptors located on T-cells that regulate immune responses at the priming phase in lymph nodes and at the effector phase in the tumor, respectively." (PMID 33805461, 2021). "Interestingly, our patient with CMMRD had TMB-H but failed to respond to anti-PD-L1 monotherapy with CS1001–101 and combined therapy of anti-PD-1 and anti-CTLA-4 monoclonal antibodies, which may be due to tumor heterogeneity and MSS status." (PMID 33422121, 2021). "Therefore, enhanced tumor immunogenicity, activated antitumor immunity, and elevated PD-1, PD-L1, and CTLA4 expression could explain why NOTCH4-MUT tumors are more likely than NOTCH4-WT tumors to benefit from immunotherapy." (PMID 34284787, 2021). "Similarly, the success of PD-1/PD-L1 and CTLA-4 checkpoint inhibitors require a competent immune system and tumor infiltration by T cells so that they may be reactivated to continue their anti-tumor response." (PMID 34298809, 2021). "Both cytotoxic T-lymphocyte-associated protein 4 (CTLA-4) and programmed death 1 (PD-1), that are induced in activated T cells providing inhibitory signals by binding to their ligands expressed on the surface of antigen presenting cells or tumor cells, are more frequently expressed." (PMID 34440802, 2021). "Similarly, we showed that miR-138 could downregulate both CTLA-4 and PD-1 to inhibit tumor-infiltrating regulatory T cells (Tregs) and in vivo administration induced tumor reduction and prolonged the survival of immune syngeneic glioma-bearing mice." (PMID 34532286, 2021). "To evaluate whether 4T1 tumor-infiltrating T cells were functionally active, we analyzed the expression of immune checkpoint inhibitory receptors PD-1 and CTLA-4, T-box transcription factor EOMES, and cytokine production of intratumor CD8+ T cells by flow cytometry." (PMID 34673569, 2021). "Therefore, immune-hot IS3 tumor with high expression of CTLA4 and PD1 may respond better to current immunotherapy which should be fully considered in immunotherapy." (PMID 34262565, 2021). "This is because JAK1 mutations modulate the tumour immune microenvironment through the depletion of TILs, which results in IFN-γ insensitivity through epigenetic silencing of interferon-signalling components, or increased expression of negative regulators such as PD-1, TIM-3, CTLA-4, and LAG-3." (PMID 34968365, 2021). "Thus TGFβ represents another potential target for anti-tumour immunotherapy and could be used in combination with anti-CTLA-4/PD-1/PD-L1 antibodies." (PMID 35069536, 2021). "Interestingly, BSJPF also significantly increased the expression of the immune checkpoint molecules PD-L1 and CTLA-4, indicating that it may alter the immune-rejection status of the tumor microenvironment and allow ccRCC patients to benefit from immunotherapy." (PMID 34002799, 2021). "Combination therapy of IL-21 with PD-1 or CTLA-4 previously showed efficacy in mouse tumour models, and an engineered IL-21 fused to a PD-1 antibody showed promising results by providing superior anti-tumour immunity than anti-PD-1 alone in preclinical studies." (PMID 34572910, 2021). "Therefore, HHLA2 may serve as a new therapeutic target for tumour immune checkpoints in addition to CTLA-4, PD-1, and PD-L1." (PMID 33962626, 2021).
tumor (continued). "In multiple syngeneic mouse tumor models, blockade of PD-1 or its ligands promoted the antitumor activity, which could be further enhanced by antibodies against other negative regulators of T-cells, such as CTLA-4 and LAG330,31." (PMID 34545109, 2021). "However, inhibiting tumoral CTLA-4 has resulted in PD-L1 upregulation and tumor relapse." (PMID 34067631, 2021). "Patients that did not respond to anti-CTLA-4 antibody ipilimumab therapy was reported to harbour mutations in the interferon gamma (IFN-γ) pathway genes leading to the ability of the tumour cells to escape from T cells, which was identified as a primary resistance to anti-CTLA-4 therapy." (PMID 34733591, 2021). "Currently, monoclonal antibodies against immune checkpoints, e.g., CTLA4, PD-1, and PD-L1, have been approved in microsatellite instability-high (MSI-H) CRCs and microsatellite-stable (MSS) tumors with high tumor mutation burden (TMB), reflecting the immunogenicity of these tumor subtypes." (PMID 34575971, 2021). "Furthermore, preclinical models using CTLA-4 blockade have shown to reduce the number of tumor-infiltrating Tregs, which could potentiate the antitumor response." (PMID 34557553, 2021). "Therefore, the combination of the CD73 inhibitor and the immune checkpoint blockade, such as CTLA-4- and PD-1 monoclonal antibody, could enhance the anti-tumor effects of these agents compared to monotherapy in several murine tumor models." (PMID 34439161, 2021). "Moreover, hypoxia can directly induce the upregulation of inhibitory immune checkpoints ligand (e.g., PD-L1 and cytotoxic T-lymphocyte-associated protein 4, CTLA-4) on dendritic cells (DCs), myeloid-derived suppressor cells (MDSCs), TAMs and tumor cells through HIF-1α." (PMID 34930293, 2021). "The discovery of the CNS lymphatic system, and previous demonstration of potential trafficking and recruitment of CD8+ T cells to the brain tissue following from PD‐1/CTLA‐4 inhibition may shed new light on the mechanism by which CAR‐T could target GBM tumor cells within the brain microenvironment." (PMID 34145792, 2021). "Likewise, previous studies have shown that both tumor-infiltrating and circulating Tregs upregulate CTLA-4 in HNSCC patients, being higher the frequency of CTLA-4+ cells on intra-tumoral Tregs as well as their immunosuppressive activity through several mechanisms involving TGF-β1." (PMID 33804419, 2021). "Normally, CTLA-4 inhibits T cells at the initial stage of naïve T-cell activation in the early stages of the immune cycle in the lymph nodes, while PD-1 regulates previously activated T cells at the later stages of an immune response in the peripheral tissues or at the tumor site." (PMID 34732257, 2021). "Interestingly, RBCK1 showed significant differential expression between cancer and normal tissues and was significantly related to tumor-infiltrating immune cells, including tumor purity and immune checkpoint molecules such as PD-L1, CTLA-4, LAG-3, and TIGIT in ccRCC." (PMID 34795663, 2021). "Hence, one might surmise that tumors harboring BRCA dysfunction and treated with PARPi could increase tumoral immunogenicity, thus sensitizing the tumor to anti-CTLA-4 antibodies." (PMID 32526888, 2020). "Therefore, RIG-I agonists have been combined with checkpoint inhibitors, with the addition of the agonist overcoming tumour resistance to anti-PD-1 and anti-CTLA4 by enhancing tumour cell death and cross-priming by cDC1s to potentiate systemic cytotoxic T lymphocyte (CTL) antitumour responses." (PMID 33352882, 2020). "Hence, treatment with anti-PD-1 and/or anti-CTLA4 antibodies may result in the additional release of Treg-mediated suppression of T cell activation, strengthening the anti-tumor immunity." (PMID 33718107, 2020).
tumor (continued). "Furthermore, preclinical and clinical studies have demonstrated that the abscopal effect of RT distinctively appeared when combined with IT, such as the presence of anti-CTLA4 or PD-1 antibodies, and anti-tumor cytotoxic T cells play a major role in that effect." (PMID 32365904, 2020). "Interestingly, we found an increased percentage of MHCII+CD11c+ DC expressing CXCL9 in the tumor mass upon administration of anti–CTLA-4 antibody and Tα1, suggesting that Tα1 can indeed modify the chemokine profile at the tumor site likely by regulating the expression program of DCs." (PMID 32817121, 2020). "Furthermore, tumor regression could be strengthened by blocking CSF-1R with a combination of PD-1 and/or CTLA-4 antibodies." (PMID 32359357, 2020). "Moreover, tumor cells can evade immune responses by exploiting immune checkpoint pathways, such as the programmed cell death-1 (PD-1) and the CTL-associated protein 4 (CTLA-4) pathways." (PMID 33298099, 2020). "Therefore, TERT mutations were closely related to a higher TMB value and unique tumor microenvironment, which may be the reason that TERT mutations may be a potential biomarker for anti‐CTLA4 treatment." (PMID 32810393, 2020). "In addition, the combination of SB-3CT and anti-CTLA-4 to treat this mouse model tumor showed similar results that substantially inhibited lung metastasis and extended the survival time of the mice with tumor metastasis to the lungs (62 days vs 19 days; p < 0.01)." (PMID 32988398, 2020). "Concerning the CTLA-4 and FoxP3 expression, although detected in both interstitial lymphocytes and tumor cells, a positive association was found only between interstitial CTLA-4 and FoxP3 expressions (R = 0.387, P = 0.01), which is negatively associated with the serum CTLA-4 levels (P = 0.03)." (PMID 32123292, 2020). "Thus, treatment with RT + IC + anti-CTLA-4 results in adaptive anti-tumor humoral memory response." (PMID 32849544, 2020). "Relief of exhaustion in tumor infiltrating lymphocytes is currently under intensive study as a therapeutic method due to significant advancements in the care of patients with melanoma, non-small cell lung cancer, and others using PD-1 and CTLA-4 checkpoint blockade." (PMID 32391270, 2020). "Furthermore, gene expression profiling of both tumor samples and peripheral T cells enabled identification of shared and non-overlapping transcriptomic changes in patients treated with anti-PD-1 and anti-CTLA-4 inhibitors." (PMID 33268350, 2020). "In addition, TIGIT, but not other checkpoint molecules, such as CTLA-4 and PD-1, was linked to NK cell exhaustion in tumor-bearing mice and patients with CRC." (PMID 33419310, 2020). "Furthermore, T cell activity is hindered owing to the expression of tumor-suppressive molecules such as PD-L1 and PD-L2 on cancer cells and CTLA-4 and PD-1 on T cells, which camouflage tumor cells from the immune system, and ultimately limit anticancer immunity." (PMID 33505987, 2020). "CTLA-4 is expressed on T regulatory cells regulating the early immune response after the primary stimulation by antigens mainly in lymphoid organs whereas PD-1 is expressed mainly on activated T cells in the tumor microenvironment regulating late immune response." (PMID 33086471, 2020). "In the experimental mouse studies in which different anti-mouse CTLA-4 monoclonal IgG antibodies (either natural or recombinant) with distinct Fc structures were compared, those with higher affinity to Fc-gamma receptors (FcγRs) showed the stronger Treg-depleting and anti-tumor activities." (PMID 32492969, 2020). "Moreover, blockade of CTLA-4 with Ipilimumab significantly activated molecular cascades that probably cooperate to create a favorable microenvironment that enhances immune responses against tumor cells." (PMID 32850353, 2020). "However, a recent study demonstrated that inhibiting autophagy might be able to sensitise PDAC tumours to dual immune checkpoint blockade (anti-PD-1 and anti-CTLA-4 antibodies)." (PMID 32635552, 2020).
tumor (continued). "Compared with the control group, the 100 mm3 (at start) group treated with the anti-CTLA-4 antibody (10 mg/kg, biw, ip) on day five showed anti-tumor activity with a statistical difference compared with the vehicle group (***P < 0.001) (the tumor volumes were 23±4 mm3 vs. 2106±205 mm3)." (PMID 32805718, 2020). "Preclinical studies targeting cytotoxic T-lymphocyte-associated protein-4 (CTLA-4), programmed death-ligand 1 (PD-L1), and indolamine 2,3-dioxygenase (IDO) have shown that therapeutic effects are associated with re-activation of CD8+ tumour-infiltrating lymphocytes (TILs) within the TME." (PMID 33121210, 2020). "Interestingly, CSF1/CSFR1 blockade achieved up to 85% tumor regression in a murine model when combined with PD1/CTLA4 inhibitors and gemcitabine, improved tumor regression in this murine model as well as increased effector CD8+ and CD4+ TIL infiltration and activity." (PMID 32823814, 2020). "At the same time, immune checkpoint molecules such as PD1 and CTLA-4 are expressed on the surface of T cells exerting the negative feedback regulation, which will induce the immune escape of tumor cells when combined with ligands expressed on the surface of tumor cells." (PMID 32280743, 2020). "Besides, inhibitory regulatory T cells (Tregs) are also associated with the tumor progression; for example, Treg secretes inhibitory cytokines, such as TGF-β and IL-10, and expresses cytotoxic T lymphocyte-associated protein 4 (CTLA4)." (PMID 33490233, 2020). "Many tumor types with poor immunological infiltration may not sensitive to CTLA-4 blockade at all; this is partly associated with the absence of tumor antigens as is the case with the challenges facing by simple PD-1/PD-L1 blockade." (PMID 33172438, 2020). "Indeed, combination of NDV with systemic anti-CTLA-4, anti-PD-1, or anti-PD-L1 resulted in enhanced rejection of bilateral tumors and prolonged animal survival compared to either treatment alone, an effect that was seen in multiple tumor types." (PMID 33260685, 2020). "In addition, blockade of CTLA-4 induced increased secretion of IL-2 by tumor cells, suggesting that the receptor regulates cellular functions that may impact the immune microenvironment." (PMID 32850353, 2020). "However, similar to other chemotherapeutic treatments, the use of immune checkpoint blockades, such as that for CTLA-4, PD-1, and PD-L1, also develops resistance to some extent, because blocking one pathway often activates the others in the complex network of tumor environments." (PMID 32847045, 2020). "Next, T cells that have successfully entered the tumor may be functionally repressed by immunosuppressive factors (like PD-L1 and CTLA-4), inhibitory cytokines (e.g., TGFβ, IL-4, and IL-10) and inhibitory cells (e.g., regulatory T cells and tumor-associated macrophages)." (PMID 32983080, 2020). "In preclinical studies, the blockade of CTLA4 led to a 1.5- to two-fold increase in the proliferation of T cells, a six-fold increase in the production of interleukin-2 and the depletion of T regulatory lymphocytes in the tumor microenvironment through a macrophage-dependent process." (PMID 32138216, 2020). "However, tumours unfortunately target CTLA-4 and PD-1 to evade T cell-mediated immunity." (PMID 33371448, 2020). "Notably, the development of a dual variable domain anti-CTLA-4 antibody, which exhibits an outer tumor antigen-binding site that hides the CTLA-4 binding region of the antibody until reaching the TME has been shown to reduce immunotherapy-induced toxicity without impeding anti-tumor immunity." (PMID 32849557, 2020). "Thus, superior results were obtained for the administration of anti-CTLA4 therapy followed by hypofractionated radiotherapy, but the anti-PD-L1 therapy demonstrates the maximum potential of radio-sensitization of the tumor in case of concomitant administration." (PMID 33374739, 2020).
tumor (continued). "Indeed, monoclonal antibodies (mAb)s targeting PD-1, PD-L1, and CTLA-4 immune checkpoints leading to increased anti-tumor response due to increased T-cell activity and proliferation, have received regulatory approval across a wide range of tumors, including NSCLC." (PMID 32760402, 2020). "Thus, CTLA-4 blockade therapy reverses the function of DCs and restores their anti-tumor activity." (PMID 32784928, 2020). "Targeting of ICOS within the context of tumor microenvironment using engineered cellular vaccines expressing ICOS ligand (ICOSL) has in particular been previously demonstrated to improve systemic efficacy of CTLA-4 blockade through potentiation of cytotoxic T cell function." (PMID 33260685, 2020). "However, co-blocking of IDO and PD-1/CTLA4 significantly abolish tumor progression." (PMID 33014820, 2020). "Consequently, it is critical to recover the NK cell's anti-tumor function by blockade of NK cell-specific checkpoint receptors or using combination blockade with NK cell checkpoint receptor and monoclonal antibodies recognizing CTLA-4 or PD-1/PD-L1." (PMID 32714324, 2020). "This study demonstrates that steroids have an inhibitory effect on anti-tumor immunity and that blocking cytotoxic T-lymphocyte-associated protein 4 (CTLA-4), but not PD-1, could partially prevent such negative modulation." (PMID 33374542, 2020). "Given the ability of β-catenin to modulate the anti-cancer immune response, we sought to determine if treatment with RX-5902 could enhance the anti-tumor activity of anti-mouse-PD-1 or anti-mouse-CTLA-4 monoclonal antibodies in an immune-competent BALB/c, 4 T1 mouse model of TNBC." (PMID 33148223, 2020). "Thus, combining adoptive transfer of Nr2f6 CRISPR/Cas9 genetically modified T cells showed synergistic effects with both the established PD-L1 and the CTLA-4 checkpoint blockade to promote tumor regression and increase survival in a subcutaneous tumor mouse model." (PMID 31937317, 2020). "Interestingly, treatment with anti-CTLA-4 was also able to induce an immune response against these Bacteroides species, which raised the hypothesis of potential molecular mimicry between tumor antigens and specific commensal bacterial species." (PMID 33062956, 2020). "In addition to the well-recognized immune checkpoints PD-1/PD-L1 and CTLA-4, more and more studies have found that tumor immune escape and drug resistance may be related to other less-appreciated immune checkpoints." (PMID 33344447, 2020). "We also examined the associations between PD-1/CTLA4 expression and the extent of tumor cell infiltration, microsatellite instability (MSI), tumor mutational burden (TMB), DNA methyltransferase (DNMT) levels, and mismatch repair (MMR) in different tumor types by gene set enrichment analysis (GSEA)." (PMID 33072070, 2020). "However, no potential association between CTLA-4 +49A/G polymorphism and tumor grade, distant metastasis, TNM stage, or histology of BC was indicated." (PMID 33335608, 2020). "Immune checkpoints [including Programmed Cell Death Protein 1 (PD-1) and Cytotoxic T-Lymphocyte-Associated Protein 4 (CTLA-4)] work when proteins on the surface of immune cells such as T cells recognize and bind to chaperone proteins (such as PD-L1) on other cells, including certain tumor cells." (PMID 32850399, 2020). "However, more recently, results from several clinical trials suggest that induction of a CD8 T cell response after CTLA-4 priming might enhance the anti-tumor efficacy of PD-1 inhibition." (PMID 32899197, 2020). "Importantly, CTLA-4 blockade monotherapy upregulated the expression of CSF-1R in tumor-infiltrating MDSCs and inhibited T cell proliferation, whereas anti-CSF-1R and CTLA-4 blockade combined treatment induced antitumor T-cell responses and tumor regression in multiple tumor models." (PMID 32942545, 2020). "Likewise, the underlying mechanisms which drive the effects of DC CTLA-4 and CTLA-4+ EVs on other dendritic cells, T-cells and anti-tumor immunity are unknown." (PMID 33384695, 2020).